PIK3R1 (phosphoinositide-3-kinase regulatory subunit 1)
Diseases named in the same sentence as PIK3R1 in open-access papers (continued):
Sharing a sentence is not in itself a finding about the gene and the disease.
breast carcinoma (continued). "Mutations in the PI3K/AKT/mTOR pathway are frequent in breast cancer, and activation of this pathway via molecular aberrations in PIK3CA, PIK3CB, PIK3R1, AKT, TSC1/2, and PTEN promotes resistance to HER2-targeted therapies." (PMID 27923043, 2016). "Liver specific loss of PIK3R1 in a murine model results in the development of aggressive hepatocellular cancer, and loss of PIK3R1 mRNA in the MCF-7 breast cancer cell line is associated with a more invasive phenotype." (PMID 26501081, 2015). "In terms of expression, PIK3R1 was underexpressed in about 90% of HR- tumors, but only in about 55% of HR + breast cancers." (PMID 24229379, 2013). "The present study focused on the prognostic roles of PIK3CA and PIK3R1 genes and additional PI3K pathway-associated genes in breast cancer." (PMID 24229379, 2013). "PIK3CA, PIK3R1 and AKT1 mutations were mutually exclusive and were observed in a total of 175 breast cancer tumors." (PMID 24229379, 2013). "The highest mutational frequency for all of the genes assessed in this study (PIK3CA and/or PIK3R1 and/or AKT1) was observed in HR+/ERBB2- tumors (133/289; 46.0%), while mutations were observed in up to 28% of cases in other breast cancer subtypes." (PMID 24229379, 2013). "On Cox multivariate regression analysis, the prognostic significance of PIK3R1 underexpression was confirmed in the total population (p = 0.0013) and in breast cancer subgroups." (PMID 24229379, 2013). "The recently observed role of PIK3R1 expression deregulation in breast cancer survival needs to be further assessed, preferably in a prospective clinical study." (PMID 24229379, 2013). "Altogether, we observed PIK3CA and/or PIK3R1 and/or AKT1 mutations in 174/454 (38.3%) breast cancer tumors." (PMID 24229379, 2013). "This suggests that p110α may represent a potential therapeutic target for treating breast cancer patients with PIK3R1 deletions." (PMID 40657399, 2025). "In addition, single-copy ablation of Pik3r1 accelerated a mouse model of HER2-/neu-driven breast cancers." (PMID 39858051, 2025). "Our findings suggest that PIK3R1 could potentially serve as a clinically valuable independent prognostic marker in breast cancer." (PMID 39850811, 2024). "It is plausible that Huangqi and Danggui activate tumor immunity by upregulating the expression of PIK3R1 in T cells, which could play a critical role in the inhibition of breast cancer." (PMID 38863309, 2024). "Moreover, studies have shown that miR-155 positively regulates glucose metabolism via the PIK3R1-FOXO3a-cMYC axis in breast cancer." (PMID 36605494, 2023). "OA likely targets PIK3R1 to overcome tamoxifen resistance in breast cancer therapy." (PMID 35482141, 2022). "Similarly, low expression levels of PIK3R1, the gene encoding the regulatory subunit of PIK3CA (p85α), have been associated to poor prognosis, in particular in breast cancer." (PMID 36110934, 2022). "PIK3R1 is missed at the mRNA expression patterns in breast cancer." (PMID 35164019, 2022). "In addition, miR-155 positively modulates glucose metabolism by the PIK3R1/FOXO3a/cMYC pathway in breast cancer." (PMID 34408553, 2021). "Furthermore, co‐mutation of PIK3R1 and PIK3CA is associated with oncogenesis and hyperactivity of the PI3K signal pathway in breast cancer, supporting an oncogenic role of the co‐mutation pair." (PMID 32419250, 2020). "Similarly, a recent study indicated miR-21 knockdown suppresses cell growth, migration, and invasion partly by inhibiting PI3K/AKT activation via direct targeting PIK3R1 in breast cancer." (PMID 32925795, 2020). "Similarly, downregulation of PIK3R1 mRNA expression is involved in migration and invasion of breast cancer cell in vitro." (PMID 31938022, 2020).
breast carcinoma (continued). "microRNA-155 positively regulates glucose metabolism via PIK3R1-FOXO3a-cMYC axis in breast cancer." (PMID 31193288, 2019). "PTEN downregulation was reported to activate PI3K/Akt pathway which may involve prolonged association between PIK3R1/p85α and the IRS-1 as well as with ErbB3, contributing to the therapy resistance in breast cancers." (PMID 31660072, 2019). "Nonetheless, it is worth studying the impact of the PIK3R1 regulatory unit in breast cancer." (PMID 30372442, 2018). "In addition, studies showed that PIK3R1 participated in the epithelial-mesenchymal transition of renal cancer cells; PIK3R1 played an essential role kidney cancer; PIK3R1 was involved in the migration and invasion of breast cancer byPI3K/AKT signaling." (PMID 30497511, 2018). "PIK3R1 encodes the regulatory subunit of PI3K (p85α), and reports in the literature have identified it as a tumor suppressor in a number of different malignancies, with low expression correlating with poor prognosis in breast cancer and renal cell carcinoma." (PMID 27608846, 2016). "Our results suggest that PIK3R1 could potentially become a clinically useful independent prognostic marker in breast cancer." (PMID 24229379, 2013). "The mutational and mRNA expression status of PIK3CA, PIK3R1 and AKT1, and expression status of other genes involved in the PI3K pathway (EGFR, PDK1, PTEN, AKT2, AKT3, GOLPH3, WEE1, P70S6K) were assessed in a series of 458 breast cancer samples." (PMID 24229379, 2013). "There is growing evidence supporting PIK3CA mutations as good prognostic markers in breast cancer, but the negative impact of PIK3R1 underexpression on patient survival has been less extensively studied." (PMID 24229379, 2013). "Furthermore, the prognostic significance of PIK3R1 underexpression persisted in the overall series (p = 0.0013) and in breast cancer subgroups characterized by ERα + (p = 0.0076), PR + (p = 0.043), ERBB2+ (p = 0.018) and also ERBB2- (p = 0.024)." (PMID 24229379, 2013). "PIK3R1 and PLCG1 are involved in intracellular signaling cascades and their differential regulation is known to be involved in tumorigenesis, while POU2F1 interacts with several known breast cancer-associated proteins (i.e. BRCA1, BARD1 and PARP1)." (PMID 17280605, 2007). "Similarly, in other cancers, PIK3R1 downregulation has been proved to be an independent prognostic marker in breast cancers and to promote propagation, migration, epithelial–mesenchymal transition, and a stem-like phenotype in renal cancer cells through the AKT/GSK3beta/CTNNB1 pathway." (PMID 31119098, 2019). "Our results divulged that breast cancer, leukemia and colorectal carcinomas were the most sensitive cancer cell types to ARQ 092 and that cell lines bearing PIK3CA/PIK3R1 mutations were more responsive to ARQ 092 (53%) compared to cells containing WT-PIK3CA/PIK3R1 (24%)." (PMID 26469692, 2015). "Moreover, when assessing breast cancer subgroups, PIK3R1 was predominantly underexpressed in HR-/ERBB2- and HR-/ERBB2+ tumors (p < 0.0000001), while PIK3CA was deregulated in only a minority of tumor samples: overexpressed in 18 (3.9%) and underexpressed in 40 (8.7%) cases." (PMID 24229379, 2013). "Other co-expressed genes such as BMF, CD53, PIK3R1, and CWF19L2 have also been reported in breast cancer studies." (PMID 40282270, 2025). "In contrast, the expression levels of PIK3R1, PNPLA2, ATOH8, TTC23, and CWF19L2 were dramatically lower in breast cancer samples than in healthy controls (p < 0.05)." (PMID 40282270, 2025). "Immunohistochemical data from the HPA database supported these findings, showing elevated PIK3R1, ESR1, and AKR1C3 levels in breast cancer tissues, aligning with their proposed roles in cancer cell proliferation and hormone regulation." (PMID 39204124, 2024). "Here, EVs from eribulin-breast cancer cells contained higher levels of PIK3R5 (log2FC = +3.877), PIK3C2B (log2FC = +1.664) and PIK3R1 (log2FC = +1.500) mRNAs than controls." (PMID 38534323, 2024).
breast carcinoma (continued). "GEPIA2 database analysis revealed significant downregulation of PIK3R1, AKR1C3, and EGFR mRNAs in breast cancer tissue, with ESR1 upregulation, pointing to a complex interplay in tumorigenesis and treatment response." (PMID 39204124, 2024). "Studies have found that Mir-21 targeting PIK3R1 can inhibit the migration and invasion of tumor cells by reducing the PI3K/AKT signaling pathway and reversing EMT in breast cancer patients." (PMID 36688087, 2023). "For breast cancer patients, known oncogenes and tumor suppressor genes such as ESR1, KRAS, PIK3CA, PIK3R1, FAT1, and MED12 were consistently identified in both ctDNA and tumor WES across patients." (PMID 37878600, 2023). "Overexpressed PIK3R1 was detected in DMBA groups treated with 7b and 14b that indicated an elevated cell apoptosis and reduced cell survival in breast cancer and confirm its effect as a tumor suppressor agent." (PMID 35164019, 2022). "The analysis of the data contained in TCGA confirmed the lower level of PIK3CA, PIK3R1 and PTEN gene expression in breast cancer tissues compared to normal tissues and a higher level of AKT1 gene." (PMID 33669698, 2021). "The analysis of the data contained in TCGA confirmed a lower level of PIK3CA, PIK3R1 and PTEN gene expression in breast cancer tissues compared to normal tissues and a higher level of the AKT1 gene." (PMID 33669698, 2021). "exon 9–10) PIK3R1, PTEN, AKT1, mTOR, was obtained using the real-time PCR technique in 54 breast cancer patients." (PMID 33669698, 2021). "In chromosome 5, we observed a narrow deletion peak involving PIK3R1 in the hg19-aligned CMT SCNAs, which has been shown to reflect arm-level losses of 5q in human breast cancer SCNAs, suggesting functional relevance in terms of PI3K-Akt signaling." (PMID 32680987, 2020). "In contrast, miR-486 inhibits cell proliferation and invasion through repressing GAB2, PIK3R1, Snail, neuropilin-2, CDK4, or PIM-1 in non-small-cell lung cancer, colorectal cancer, prostate cancer, hepatocellular carcinoma, and breast cancer cells." (PMID 32155804, 2020). "Importantly, silencing of PIK3R1 in breast cancer could enhance the sensitivity to rapamycin." (PMID 31938022, 2020). "Consistently, inhibiting p300/CBP substantially decreased CapG-dependent upregulation of PIK3R1/P50 and subsequent PI3K/Akt activation, resulting in increased sensitivity to paclitaxel treatment in breast cancer cells." (PMID 31660072, 2019). "In contrast, MCM4 gene promoter was hypermethylated in breast cancer and BCL2, PIK3R1 gene promoter were hypomethylated." (PMID 31777591, 2019). "It has been reported that miR-21 suppresses breast cancer cell migration and reverses EMT through targeting PIK3R1 via PI3K/Akt signaling pathway." (PMID 28900284, 2017). "The hub targets identified for SRC, PIK3R1, PIK3CA, STAT3, and EGFR may represent significant therapeutic targets for the treatment of breast cancer using TSAC." (PMID 40864816, 2025). "Notably, PIK3R1, AKR1C3, and EGFR mRNAs were significantly downregulated in breast cancer tissue, while ESR1 was significantly upregulated." (PMID 39204124, 2024). "To note, the protein–protein interaction network of PIK3R1, IL1R1, MMP11, GOLM1, and VAV3 altogether connected by EGFR merits further work to understand the mechanism and develop an ideal treatment strategy for invasive small tumor-size breast cancers." (PMID 39190284, 2024). "Overexpression of all analyzed mRNA transcripts, expect PIK3R1 was observed in cancerous tissues compared to controls, with the highest increase in transcriptional activity noted in triple-negative breast cancer (TNBC) compared to other breast cancer types." (PMID 39850811, 2024). "It was stated that the average expression level of the PIK3CA, PIK3R1, PTEN genes in the group of breast cancer patients is lower in comparison to the control group, while the average expression level of the AKT1 and mTOR genes in the studied group was higher in comparison to the control group." (PMID 33669698, 2021).
breast carcinoma (continued). "In order to extend the knowledge, we assessed the prevalence of the E542K, E545K, H1047R mutations within the PIK3CA gene and the E17K mutation within the AKT1 gene, and the expression of the PIK3CA, PIK3R1, PTEN, AKT1, mTOR genes in a cohort of patients with breast cancer." (PMID 33669698, 2021). "We found CapG specifically promoted PIK3R1/P50 isoform transcription in breast cancer cells, which subsequently triggered activation of PI3K/Akt signaling, resulting in increased cell growth and decreased apoptosis in breast cancer cells exposed to paclitaxel." (PMID 31660072, 2019). "Collectively, these findings strongly indicate that CapG-facilitated enrichment of CBP/p300 at PIK3R1/P50 promoter and increased H3K27 acetylation are essential for induction of PIK3R1/P50 transcription and subsequent PI3K/Akt activation in breast cancer cells." (PMID 31660072, 2019). "The frequencies of PIK3CA, PIK3R1 and AKT1 alteration differ according to breast cancer subtypes." (PMID 24229379, 2013). "These tumors cluster with non-tumoral breast cancer cells and exhibit over-expression of PIK3R1 and AKR1C1, in addition to other genomic alterations." (PMID 20492711, 2010). "Moreover, miR-21's targeting of PIK3R1 inhibits tumor cell migration and invasion by reducing PI3K/AKT signaling, reversing epithelial-to-mesenchymal transition, and predicting clinical outcomes in breast cancer." (PMID 40657399, 2025). "Therefore, selective upregulating of PIK3R1/p50α, instead of p85α, by CapG may lead to more efficient activation of PI3K/Akt activation in breast cancer cells." (PMID 31660072, 2019). "Most biological functions in the MCF7 network are controlled by the PIK3R1 gene, and many other pathways, including apoptosis, ErbB, JAK–STAT, HIF-1, the control of the actin cytoskeleton, TNF, cancer-related pathways, TCR, BCR, and TLR signaling pathways, may also be related to breast cancer." (PMID 36675976, 2022). "The immunohistochemical findings presented in the Human Protein Atlas (HPA) database indicated elevated levels of PIK3R1, ESR1, and AKR1C3 in breast cancer tissues as opposed to normal tissues." (PMID 39204124, 2024).
Insulin resistance (48 papers, 2008 to 2025). Increased resistance towards insulin, that is, diminished effectiveness of insulin in reducing blood glucose levels. "Germline PIK3R1 variants are associated with varying phenotypes, including immunodeficiency or facial dysmorphism with growth delay, lipoatrophy, and insulin resistance associated with SHORT syndrome." (PMID 38541623, 2024). "We report the case of a Chinese adult female patient with SHORT syndrome, carrying a PIK3R1 gene variant (c.1945C > T), who developed abnormal glucose metabolism and severe postprandial insulin resistance over 9 years." (PMID 39735640, 2024). "Several works of research have indicated that PIK3R1 mutations are the second common origin in the rank of single-gene insulin resistance." (PMID 37664840, 2023). "Phosphoinositide-3-kinase (PI3K) plays an important role in the metabolic actions of insulin and a mutation in the PIK3R1 gene has been associated with insulin resistance." (PMID 36269347, 2023). "Currently, there are around 10 mutations in PIK3R1 confirmed to be associated with SHORT syndrome that contribute to insulin resistance and/or lipodystrophy." (PMID 37628845, 2023). "The diet/VF-DMPs annotated to 12 genes, with fibre, DASH and DQI-I all showing differential methylation in PIK3R1 which is associated with insulin resistance." (PMID 35843982, 2022). "In parallel, it was shown that PIK3R1 (p85α) expression was increased in type 2 diabetes and was associated with insulin resistance through PI 3-kinase mechanisms." (PMID 35906673, 2022). "PIK3R1 encodes an enzyme with a direct role in insulin signalling and individuals with mutations in PIK3R1 show severe insulin resistance." (PMID 35843982, 2022). "The mutation of PIK3R1 relating to insulin resistance can affect both cardiac metabolism and contractile function." (PMID 33015184, 2020). "Mutations in the PIK3R1 gene have been linked to insulin resistance, cancer, and immunodeficiencies." (PMID 33221758, 2020). "The panel covered most of the SHORT syndrome-associated PIK3R1 coding region mutations currently identified, as well as PIK3R1 mutations associated with colorectal cancer risk and with insulin resistance (HGMDR Human Gene Mutation Database)." (PMID 28143957, 2017). "In the pathogenesis of T2DM, mutations or malfunctions of the PIK3R1 gene may lead to insulin resistance, which is an important component of T2DM pathogenesis." (PMID 40747301, 2025). "Mutations in PIK3R1 are directly associated with insulin resistance and T2D." (PMID 41465472, 2025). "Pathogenic variants of PIK3R1 have been associated with insulin resistance." (PMID 40823947, 2025). "Therefore, our results indicate that miR-153-3p, via PIK3R1, causes insulin resistance in the brain, and is involved in CS-induced neurotoxicity." (PMID 38133370, 2023). "PIK3R1 mutations in humans result in severe insulin resistance and PI3K-dependent signaling." (PMID 36159557, 2022). "Human genomic studies have associated Pik3r1 to insulin resistance." (PMID 33567340, 2021). "Mutations of PIK3R1 could cause insulin resistance, which is strongly associated with insulin resistance." (PMID 32143602, 2020). "We next assessed whether the 4 additional patients with PIK3R1 mutations shared the insulin resistance subphenotype of the proband." (PMID 27766312, 2016). "In view of the discordance in plasma adiponectin values between P1 and the 3 other patients with PIK3R1 mutations and extreme insulin resistance, we reexamined the exome sequence of P1 to determine whether there were any sequence variants in the ADIPOQ gene, encoding adiponectin." (PMID 27766312, 2016). "In summary, our findings establish that in humans, C-terminal SH2 domain mutations in PIK3R1 produce a metabolic phenocopy of insulin receptor dysfunction, with strikingly preserved liver fat, lipid profile, and plasma adiponectin despite severe insulin resistance." (PMID 27766312, 2016).